HSP90AA1 (heat shock protein 90 alpha family class A member 1)
Diseases named in the same sentence as HSP90AA1 in open-access papers (continued):
Sharing a sentence is not in itself a finding about the gene and the disease.
osteosarcoma (continued). "And HSP90AA1, acting as an important regulator of autophagy, is a critical factor in the development of osteosarcoma chemoresistance both in vitro and in vivo." (PMID 30153855, 2018). "Doxorubicin, cisplatin, and methotrexate, which are commonly used in chemotherapy, each induced HSP90AA1 upregulation in human osteosarcoma cells." (PMID 30153855, 2018). "In the present study, we observed an increase in phosphorylation of JNK and p38 in HSP90AA1 shRNA transfected osteosarcoma cells." (PMID 30153855, 2018). "Suppression of HSP90AA1 or blockade of autophagy increased the drug sensitivity of osteosarcoma cells." (PMID 30153855, 2018). "mRNA and protein expressions of HSP90AA1 in osteosarcoma cells were tested by quantitative real-time PCR and western blot, respectively." (PMID 30153855, 2018). "We analyzed the expression of HSP90AA1 in osteosarcoma cell lines exposed to chemotherapy agents cisplatin (Cis), doxorubicin (Dox), and methotrexate (Mtx)." (PMID 30153855, 2018). "Suppression of HSP90AA1 diminished autophagic protection in response to chemotherapy in osteosarcoma cells." (PMID 30153855, 2018). "In the present study, we found that HSP90AA1 is upregulated during chemotherapy and the autophagy mediated by it contributes to chemotherapy resistance in osteosarcoma both in vivo and in vitro." (PMID 30153855, 2018). "In this study, we demonstrated that HSP90AA1 gene is responsible for drug resistance in osteosarcoma through an autophagy-related mechanism." (PMID 30153855, 2018). "In this study, we evaluated the autophagy activity in osteosarcoma cells after treatment with chemotherapy and found that knockdown of HSP90AA1 blocked the autophagic flux detected by mRFP-GFP-LC3 construct." (PMID 30153855, 2018). "HSP90AA1 mediating autophagy contributes to chemotherapy resistance in osteosarcoma." (PMID 40727105, 2025). "In past studies, HSP90AA1 expression also favoured chemoresistance in osteosarcoma and distant metastasis in hepatocellular carcinoma by a mechanism that may be connected to PI3K/Akt/mTOR signaling and epithelial mesenchymal transition." (PMID 38263419, 2024). "Extensive research currently delves into the potential role of individual HSPs such as HSPB1, HSPBP1, and HSP90AA1 in influencing the survival and advancement of osteosarcoma, yet the prognostic value and molecular mechanisms of other HSP family members in osteosarcoma remain to be elucidated 72-77." (PMID 39430254, 2024). "Hence, in order to improve the survival rate of osteosarcoma through overcome chemoresistance, our focus here was the interaction between HSP90AA1 and autophagy." (PMID 30153855, 2018). "We showed that chemotherapy agents can induce HSP90AA1 expression in osteosarcoma cells." (PMID 30153855, 2018). "Therefore, it would be important to determine the role of HSP90AA1 in osteosarcoma cells with a particular focus on autophagy and its potential effects on the drug resistance." (PMID 30153855, 2018). "shRNAs were transfected into osteosarcoma cells for knockdown of HSP90AA1 gene." (PMID 30153855, 2018). "To determine whether HSP90AA1 regulates autophagy, we evaluated autophagy activity in osteosarcoma cells after treatment with chemotherapy agents." (PMID 30153855, 2018). "HSP90AA1 provides a novel therapeutic target for improving osteosarcoma treatment." (PMID 30153855, 2018). "We firstly observed that cisplatin, doxorubicin and methotrexate promoted the expression of HSP90AA1 in human osteosarcoma cells, suggesting that HSP90AA1 may correlate with chemotherapy resistance." (PMID 30153855, 2018). "In conclusion, here we showed chemotherapy agents induce HSP90AA1 expression in osteosarcoma cells." (PMID 30153855, 2018). "Taken together, these findings suggest that HSP90AA1 promotes autophagy in osteosarcoma cells." (PMID 30153855, 2018). "Importantly, we found that inhibition of autophagy promotes osteosarcoma cell apoptosis and reverses HSP90AA1-mediated drug resistance." (PMID 30153855, 2018).
osteosarcoma (continued). "This detailed understanding of autophagy regulated by HSP90AA1 in osteosarcoma might contribute to predicting and overcoming chemoresistance, thereby improving the therapeutic efficacy and overall survival of osteosarcoma patients." (PMID 30153855, 2018). "However, little is known about the role of HSP90AA1 in autophagy and in osteosarcoma drug resistance." (PMID 30153855, 2018). "However, whether HSP90AA1 regulates autophagy when osteosarcoma cells subjected to chemotherapy and the effect of HSP90AA1 on drug resistance in osteosarcoma remain unknow." (PMID 30153855, 2018). "Consistent with the network pharmacology results, the RT-PCR experiments showed significant downregulation of JUN, HSP90AA1, HDAC1, and CDK1 expression by TGT, highlighting their potential significance as targets in the anti-osteosarcoma mechanism of TGT." (PMID 38297292, 2024). "By suppressing the activities of JUN, HSP90AA1, HDAC1, and CDK1, TGT can impede the growth of osteosarcoma cells." (PMID 38297292, 2024). "Recent evidence confirmed that the heat shock protein HSP90AA1 independently acted on the PI3K/AKT/mTOR and JNK/P38 signaling pathways to trigger autophagy in osteosarcoma cells." (PMID 36359776, 2022). "Silencing the HSP90AA1 gene reduces LC3II expression but increases Beclin-1 expression, thus enhancing the sensitivity of osteosarcoma cells to CDDP, DOX and methotrexate-based chemotherapy." (PMID 36359776, 2022). "PPI results showed that EGFR, CASP3, ESR1, HSP90AA1, and SRC may be potential targets for PA against osteosarcoma." (PMID 40991530, 2025). "Among these core targets, EGFR (48-sided), CASP3 (47-sided), ESR1 (42-sided), HSP90AA1 (42-sided), SRC (42-sided) and IGF1 (40-sided) have high nodes, indicating that they are closely associated with PA anti-osteosarcoma dense mechanisms." (PMID 40991530, 2025). "HSP90AA1 is also an important regulator of autophagy that promotes autophagy by mediating the PI3K/Akt/mTOR cascade and inhibits cell apoptosis through the JNK/P38 pathway in osteosarcoma." (PMID 39006030, 2024). "HSP90AA1, as an important regulator of autophagy, promoted autophagy through the PI3K/Akt/mTOR pathway, inhibited apoptosis through the c-Junction N terminal kinase (JNK)/P38 pathway, and was a critical factor in the development of osteosarcoma chemoresistance." (PMID 38713284, 2024). "Additionally, HSP90AA1 can promote autophagy through the PI3K/Akt/mTOR signaling pathway, and inhibit apoptosis through the JNK/P38 signaling pathway to improve the drug resistance of osteosarcoma cells." (PMID 37999247, 2023). "Moreover, among our predicted targets, such as HSP90AA1, HSP90B1, which are related to the protein synthesis process, so we hypothesize that SS acts on the targets to regulate protein synthesis, which in turn affects the progression of osteosarcoma." (PMID 40831924, 2025).
prostate carcinoma (21 papers, 2014 to 2025). A carcinoma that arises from epithelial cells of the prostate gland. "One mechanism by which circRNF19A-490aa promotes the malignant phenotype of prostate cancer cells is through binding to HSP90AA1, which in turn activates hallmark pathways such as the PI3K/AKT pathway." (PMID 39567496, 2024). "Some of the genes that have been linked to the development of prostate cancer are PIK3R1, SRC, STAT3, HSP90AA1, AKT1, MAPK1, SESR1, and AR." (PMID 39114070, 2024). "The binding of HSF1 to the HSP90AA1 gene promoter region was increased in response to HSS in PC-3 prostate cancer cells." (PMID 36982267, 2023). "Ectopic expression of miR550a-3p in DMPM, ovarian cancer, and prostate cancer cell lines consistently decreased HSP90AA1 expression at both mRNA and protein levels." (PMID 35352023, 2022). "Hsp90AA1 is expressed in various cancers, including breast, colon, ovarian, lung and prostate cancers." (PMID 32523426, 2020). "In contrast, HSP90AA1 is responsible for the degradation of androgen receptor and cell killing following radiation exposure in a prostate cancer cell line." (PMID 25313363, 2014). "Our pathway analysis further supports the roles these three molecules play in carcinogenesis by mapping the interaction among hsa-miR185-5p, TCF7, and HSP90AA1 to prostate cancer through the PI3K signaling pathway." (PMID 25313363, 2014). "HSP90AA1 is expressed highly in most cancers, but poorly in prostate cancer tissue." (PMID 35594510, 2022). "Analysis indicated that the 9 hub genes (AKT1, HSP90AA1, SRC, GSK3β, VEGFR2, RHOA, ENO1, PKM, and IL-2) play roles in MF treatment by participating in signaling pathways related to prostate cancer, lipid and atherosclerosis, and insulin resistance." (PMID 40051434, 2025). "In the immune cell cluster of prostate cancer, formononetin targeted CD74, TNF, HBB, THBS1, INSR, CXCR4, and HSP90AA1." (PMID 38874510, 2024). "High expression of HSP90AA1 correlated with poorer prognoses in several cancer types, although SCAND1 and MZF1 blocked the heat shock responsiveness of HSP90AA1 in prostate cancer cells." (PMID 36982267, 2023). "Stigmasterol, isoboldine, and β-sitosterol could target key prostate cancer-related hub genes (e.g., SRC, FGFR1, HSP90AA1); stigmasterol showed the strongest binding to HSP90AA1, and pathway analysis highlighted involvement of PI3K/AKT signaling." (PMID 41158126, 2025). "Although it was suggested that HSP90AA1 could be a potential target for NSCLC treatment, another protein-coding gene, NCOA2, might be relevant for gastric cancer, liver cancer, or prostate cancer." (PMID 35256890, 2022).
COVID-19 (19 papers, 2020 to 2024). A disease caused by infection with severe acute respiratory syndrome coronavirus 2. "Within the confines of the COVID-19 dataset, the HSP90AA1 gene demonstrated commendable diagnostic efficacy (AUC: 0.745) in discriminating individuals afflicted by SARS-CoV-2 from their healthy counterparts." (PMID 38443855, 2024). "Moreover, HSP90AA1 was identified as a risk factor for the coexistence of COVID-19 and cardiovascular disease." (PMID 38443855, 2024). "HSP90AA1 was found to be a risk factor for the combination of cardiovascular disease and COVID-19." (PMID 37047484, 2023). "We undertook a comprehensive analysis of the intricate interrelationship existing between HSP90AA1 and immune cell populations, both in the context of COVID-19 and OSA." (PMID 38443855, 2024). "The finding of proteomics unveiled a substantial augmentation in the expression level of HSP90AA1 in COVID-19 patient samples, especially in severe conditions." (PMID 38443855, 2024). "Our findings unveiled a notable escalation in the plasma concentration of HSP90AA1 in the context of more severe manifestations of COVID-19." (PMID 38443855, 2024). "We therefore concluded that HSP90AA1, HSPA9, and SRSF1 are pivotal genes in the co-morbidity of COVID-19 and ICM and have considerable diagnostic value." (PMID 37047484, 2023). "In order to investigate HSP90AA1 mRNA deregulation in patients infected with COVID-19, we re-examined the BAL scRNA-seq." (PMID 33585804, 2021). "The PPI network analysis exhibits that numerous genes, including IL-6, TNF-α, MAPK3, MAPK1, AKT1, mTOR, HIF1A, HSP90AA1, EGFR, CASP3, etc., are implicated in the pathogenicity of COVID-19 disease and also in the anti-COVID-19 effects of Meliae cortex’s key active phytonutrients." (PMID 36817449, 2023). "In this study, through network pharmacology, molecular docking, target analysis, and tissue analysis, it can be concluded that Xiyanping injection and andrographolide sulfonates such as compound III in the treatment of COVID-19 mainly act on HSP90AA1, CAT, TNF, FOS, and other targets." (PMID 35818408, 2022). "It acts on protein targets such as HSP90AA1 and plays a potential therapeutic role in COVID-19." (PMID 35818408, 2022). "Differential expression of HSP90AA1 in a co-expression network reported in severe COVID-19 cases and the MAPK pathway play a crucial role in SARS-CoV-2 infection where p38 MAPK could be a potential target." (PMID 34067609, 2021). "Moreover, we embarked on an exploration of the prognostic implications encapsulated within the HSP90AA1 proteins present within clinical serum samples originating from diverse COVID-19 cases, each marked by disparate outcomes (Fatal (F) = 20, Severe (S) = 14, Mild (M) = 20, Healthy (H) = 7)." (PMID 38443855, 2024). "The top 10 of 41 potential anti-COVID-19 core targets (AKT1, TNF, HSP90AA1, IL-6, mTOR, EGFR, CASP3, HIF1A, MAPK3, and MAPK1) were identified as molecular targets of key active phytonutrients of the Meliae cortex that might be implicated in ameliorating COVID-19." (PMID 36817449, 2023). "Nine of ten anti-COVID-19 core targets (HIF1A, EGFR, CASP3, AKT1, MAPK1, MAPK3, HSP90AA1, mTOR, and IL-6) followed the pathways in cancer." (PMID 36817449, 2023).
COVID-19 (continued). "The top three Meliae cortex’s key active phytonutrients were further analyzed for molecular docking with the top ten anti-COVID-19 core targets, including AKT1, TNF, HSP90AA1, IL-6, mTOR, EGFR, CASP3, HIF1A, MAPK3, and MAPK1." (PMID 36817449, 2023). "The top ten anti-COVID-19 core targets, AKT1, TNF, HSP90AA1, IL-6, mTOR, EGFR, CASP3, HIF1A, MAPK3, and MAPK1, were chosen for molecular docking studies with the Meliae cortex’s key active phytonutrients determined in section 3.7." (PMID 36817449, 2023). "In this study, HSP90AA1, HSPA9, and SRSF1 were identified as markers for the co-pathogenesis of COVID-19 and ICM." (PMID 37047484, 2023). "A previous study found that Jin Hua Qing Gan Granules regulate multiple signaling pathways via binding targets, such as PTGS2, HSP90AA1, and NCOA2, to prevent COVID-19." (PMID 35891565, 2022). "In addition, cluster 1 confirms the existence of the top ten potential anti-COVID-19 core targets (AKT1, TNF, HSP90AA1, IL-6, mTOR, EGFR, CASP3, HIF1A, MAPK3, and MAPK1); consequently, the results of the PPI and cluster network analyses are congruent." (PMID 36817449, 2023). "We identified HSP90AA1, HSPA9, and SRSF1 as markers for the co-pathogenesis of ICM and COVID-19, and showed that co-pathogenesis of ICM and COVID-19 may be related to angiogenesis." (PMID 37047484, 2023). "Despite the failure of docking with SRSF1, the docking of vindesine and ON-01910 with HSP90AA1 and HSPA9 tentatively validated the feasibility of these drugs binding to the hub genes, indicating that vindesine and ON-01910 may be disease-specific agents of ICM and COVID-19." (PMID 37047484, 2023). "We identified the heat shock protein 90 alpha family class A member 1 (HSP90AA1) hub-high traffic gene in the pink module, which has an important role in development of SARS-CoV-2 infection and has a significant increase in expression in severe COVID-19 patients compared to the non-severe group." (PMID 34975885, 2021).
hepatocellular carcinoma (17 papers, 2017 to 2026). A malignant tumor that arises from hepatocytes. "HSP90AA1 is associated with poor prognosis in hepatocellular carcinoma and contributes to tumorigenesis and chemoresistance." (PMID 40649911, 2025). "For example, HSP90AA1 is an unfavorable prognostic factor for hepatocellular carcinoma (HCC) and can lead to tumor development and chemotherapy resistance." (PMID 41507145, 2026). "NAT10 mediates HSP90AA1 ac4C acetylation to promote endoplasmic reticulum stress‐mediated hepatocellular carcinoma metastasis and lenvatinib resistance." (PMID 39640362, 2024). "In another study, FBXL6 played an important role in promoting hepatocellular carcinoma owing to the ubiquitination and stabilization of HSP90AA1, which contributed to tumorigenesis in hepatocellular carcinoma." (PMID 36685928, 2022). "HSP90AA1 stabilizes and activates c-Myc and participates in the occurrence of colorectal carcinoma and hepatocellular carcinoma." (PMID 34557405, 2021). "In conclusion, HSP90AA1 may be a key molecule of SFN in the development of hepatocellular carcinoma, which plays a role through protein interaction and subsequent changes in signal pathway status." (PMID 33491737, 2021). "In hepatocellular carcinoma, NAT10 activates the endoplasmic reticulum stress axis while concurrently upregulating ac4C modification levels of HSP90AA1 mRNA, thereby increasing HSP90AA1 protein expression." (PMID 40881352, 2025). "HSP90AA1 and HSPA1A were detected at the surface of tumor cell lines (microcitoma, lung carcinomas, melanomas, Ewing’s sarcomas, osteosarcomas and hepatomas)." (PMID 28468249, 2017). "NAT10 could upregulate the modification level of HSP90AA1 mRNA ac4C, maintain the stability of HSP90AA1, and upregulate the expression of HSP90AA1, which further promotes the metastasis of ERS hepatoma cells and the resistance to apoptosis of Lenvatinib." (PMID 36765042, 2023). "Tumor cell lines, such as hepatocellular carcinoma cell line HepG2 and murine leukemia monocytes cell lines, were described to secrete HSPD1, HSPA1A, and HSP90AA1 in exosomes, which augmented the cytolytic activity of natural killer cells, macrophages and mononuclear cells." (PMID 28468249, 2017).